MTOR (mechanistic target of rapamycin kinase)
Diseases named in the same sentence as MTOR in open-access papers (continued):
Sharing a sentence is not in itself a finding about the gene and the disease.
prostate carcinoma (continued). "A critical characteristic of prostate cancer is the oncogenic activation of the mammalian target of rapamycin (mTOR) pathway, which facilitates the initiation, progression and therapeutic resistance of prostate cancer." (PMID 38273337, 2024). "Mitochondrial unfolded protein response inhibitors targeting HSPD1 induced accumulation of poly-ubiquitinated proteins and metabolic stress, thereby suppressing AKT/mTOR signaling in prostate cancer." (PMID 39430254, 2024). "For upregulated miRNAs in EBV-positive PCa tissues, we observed enrichment of pathways related to renal cell carcinoma (RCC), miRNAs in cancer, prostate cancer, chronic myeloid leukemia, Ras, MTOR, and PI3K-Akt signaling pathways, among others." (PMID 38705879, 2024). "Exendin-4 further reverses prostate cancer growth and invasion by counteracting benzalutamide-mediated activation of Akt and mTOR, followed by down-regulation of S6K and 4EBP-1, ultimately reversing the resistance of prostate cancer to benzalutamide." (PMID 39465848, 2024). "Garcinol has been previously found to reduce the expression of cyclin D1 in endometrial, gastric, and colon cancers, as well as inhibit the expression of mTOR in human prostate cancer cells and xenograft." (PMID 37577271, 2023). "Ellagic acid can also inhibit cell proliferation and induce apoptosis in prostate cancer cells by regulating the Akt and mTOR pathways." (PMID 37571251, 2023). "In most prostate cancer cell lines, the PIP3 phosphatase PTEN, which antagonizes this pathway, is mutated and therefore the PI3K/Akt/mTOR pathway is activated." (PMID 37958610, 2023). "Using polysome profiling in prostate cancer cells, the translation of 144 mRNAs were identified as dependent on mTOR activity (Hsiehet al., 2012)." (PMID 38628976, 2023). "In prostate cancer, increasing p-mTOR expression was demonstrated that has positive correlations with lymphangiogenesis and lymphatic metastasis." (PMID 37416763, 2023). "The results suggest that glutamic and aspartic acid are involved in calcium and phospholipid binding as determinants of ANXA7 action on IP3 receptor expression and prostate cancer cell survival acting via the PI3K/mTOR pathway." (PMID 37240163, 2023). "In prostate cancer, increased ALDH1A3 activated the phosphatidylinositol 3-kinase/Protein kinase B/rapamycin (PI3K/AKT/mTOR) signaling pathway conferred a survival advantage to prostate cancer cells and decreasing their sensitivity to docetaxel." (PMID 36672441, 2023). "Suppressor APC domain containing neuroblastoma (SAPCD2), has been reported to regulate Yap/Taz, MAPK, and mTOR signaling in various cancers, including colorectal and prostate cancer." (PMID 37705968, 2023). "Other research has found that miR-100-5p can be involved in autophagy through targeting mTOR in stroke, prostate cancer, and neurodegeneration." (PMID 37610710, 2023). "The CXCR6‐CXCL16 axis also promotes docetaxel resistance through phosphorylation of GSK‐3β, NF‐κB and ERK1/2, as well as angiogenesis in prostate cancer via AKT/mTOR‐mediated regulation of VEGF and IL‐8." (PMID 36608258, 2023). "It was shown that treatment with S1P in PC3 prostate cancer cells can induce autophagy through the inhibition of mTOR." (PMID 37190124, 2023). "Curcumin inhibits cancer-associated fibroblast-driven prostate cancer invasion, EMT, ROS production, and decreased CXCR4 and IL-6 receptor expression through MAOA/mTOR/HIF-1α signaling." (PMID 38008819, 2023). "LncRNA PRRT3-AS1 is able to inhibit the PPARγ gene to promote prostate cancer cell proliferation and inhibit apoptosis and autophagy by activating the mTOR signaling pathway." (PMID 36647032, 2023). "Reduced INPP4B levels are seen in prostate cancer, and overexpression leads to the inactivation of the PI3K/AKT/mTOR pathway and suppression of prostate cancer cell migration and invasion." (PMID 36768610, 2023).
prostate carcinoma (continued). "This follow-up screen provided validation of inhibitors of JAK/STAT and PI3K/mTOR as therapeutic vulnerabilities for both Snail+ and enzalutamide-resistant prostate cancer." (PMID 37228586, 2023). "PTEN is a tumor suppressor that tightly regulates the phosphoinositide-3-kinase/serine-threonine kinase/mammalian target of rapamycin (PI3K/AKT/mTOR) signaling axis, which is the main survival pathway involved in prostate cancer." (PMID 37305830, 2023). "Among the inhibited pathways, the involvement of the miRNA set in cell growth (mTOR signaling pathway) and various cancer entities (such as prostate carcinoma, melanoma) was noteworthy." (PMID 38003618, 2023). "Several studies have confirmed that activation of the PI3K/AKT/mTOR pathway plays a vital role in the occurrence and development of prostate cancer." (PMID 37313467, 2023). "Activation of mTOR in CSCs has been reported in various cancers, such as colon cancer, prostate cancer, salivary gland cancer, and glioblastoma." (PMID 36816969, 2023). "The zinc finger homeobox protein 3 (ZFHX3) is a transcription factor often mutated in prostate cancer and it suppresses PI3K/AKT/mTOR signaling." (PMID 36768610, 2023). "As mentioned, prostate cancer growth is particularly dependent on altered lipid metabolism, a process controlled at least in part by mTOR." (PMID 36768610, 2023). "It inhibits the PI3K/Akt and mTOR pathways in humans and is therefore important for managing prostate cancer." (PMID 37240765, 2023). "PTEN has been reported to be lost or mutated in most advanced prostate cancer cases and there are numerous inhibitors in development that target various PI3K cascade nodes, including PI3K, AKT, mTOR." (PMID 36835033, 2023). "mTOR is deregulated in nearly 100% of advanced human prostate cancers, and genetic studies in mouse models suggest that mTOR is overactivated during prostate cancer initiation." (PMID 37049920, 2023). "To detect the possible mTOR involvement in the tumor suppressor effects of ANXA7 in prostate cancer cells, we juxtaposed the microarray-derived mTOR gene expression and apoptotic rates based on PS exposure and cell membrane permeabilization (ANXAV-PE)." (PMID 37240163, 2023). "For instance, TIA was proposed to interfere with mTOR function and induce ER stress in breast and prostate cancer cells." (PMID 37175205, 2023). "Down-regulated pathways in C2 subtype (thereby up regulated in C3 subtype) included Notch signaling, breast/endometrial/prostate cancer signaling pathways, mTOR, and FoxO signaling pathways." (PMID 36980321, 2023). "Prostate cancer tissues were found to have overactivated mTOR when compared to normal prostate epithelium." (PMID 37108576, 2023). "The results suggest that the glutamic and aspartic acid residues involved in calcium and phospholipid binding serve as the determinants of ANXA7 action on IP3 receptor expression and prostate cancer cell survival via the PI3K/mTOR pathway." (PMID 37240163, 2023). "Preclinical studies hint that almost all recurrent prostate cancers develop aberrant mTOR-pathway signaling." (PMID 37623437, 2023). "Next the contribution of Akt-mTOR inhibition on SKI-178-induced anti-prostate cancer cell activity was studied." (PMID 37604912, 2023). "Cav1 mainly affects the occurrence of prostate cancer through AKT/mTOR, H-RAS/PLCε, CD147/MMPs and other pathways, as well as substance metabolism including lipid metabolism and aerobic glycolysis." (PMID 37910338, 2023). "Studies of prostate cancer have shown that the most common targets of increased translation through mTOR are those involved in invasion, metastasis, and protein synthesis." (PMID 37049920, 2023). "Auraptene activates AMPK and suppresses the mTOR/S6K pathway, as well as inhibiting the proliferation and migration of prostate cancer cells." (PMID 37958994, 2023).
prostate carcinoma (continued). "CAFs enhanced the EMT process by activating the MAOA/mTOR/ HIF1α signaling axis and enhanced the migration and invasion abilities of prostate cancer cells." (PMID 35589690, 2022). "Genetic alteration of the PI3K/AKT/mTOR pathway is one of the key events in tumor development and progression in prostate cancer, with inactivation of the PTEN tumor suppressor being very common in this cancer type." (PMID 35086953, 2022). "PRRT3-AS1 silencing can upregulate apoptosis and autophagy while diminishing the proliferation, migration, and invasion of prostate cancer cells via the mTOR signaling pathway." (PMID 36105104, 2022). "Tangeretin was evaluated for anti-prostate cancer potential targeting the PI3K/Akt/mTOR signaling pathway." (PMID 35795855, 2022). "In vitro, in vivo, and ex vivo antiangiogenic potential of quercetin reported that the progression of human prostate cancer was suppressed through the regulation of VEGFR-2-mediated Akt/mTOR/P70S6K signaling pathways." (PMID 36233051, 2022). "In this study, we have investigated the response of PTEN wild-type prostate cancer cell lines to the dual PI3K/mTOR inhibitor DS-7423 alone or in combination with HER2 inhibitors or mGluR1 inhibitors." (PMID 35086953, 2022). "It has been proven that autophagy in human prostate cancer cells is induced by PKM2 knockdown via the Akt/mTOR pathway, and a specific PKM2 inhibitor, compound 3K, also promoted the cell death of SK-OV-3 via restraining the Akt/mTOR pathway." (PMID 36612260, 2022). "Its depletion suppressed the proliferation and the motility of prostate cancer cells via mediating PI3K/Akt/mTOR pathway." (PMID 36448058, 2022). "The mammalian target of the rapamycin (mTOR) signaling pathway is also altered in prostate cancer, which enables proliferation and survival of tumoral cells." (PMID 36365241, 2022). "Branched chain amino acids can possibly work as precursors for citrate production, and leucine can act as a sensor for mTOR-pathway activation, which is generally regarded as an important pathway in prostate cancer development." (PMID 35707723, 2022). "Combination of PI-103 and mTOR inhibitor rapamycin performed a better therapeutic effect than single agents in human ovarian and prostate cancer cells, and can effectively prevent rebound activation of the Akt pathway after rapamycin treatment." (PMID 35918352, 2022). "YVPGP, an Anthopleura anjunae-derived peptide, shows antiproliferation against prostate cancer cells by inactivating PI3K/AKT/mTOR." (PMID 36139919, 2022). "Silencing PRRT3-AS1 upregulates the expression level of PPARG/PPARγ (peroxisome proliferator activated receptor gamma) that, in turn, inhibits MTOR signaling, leading to autophagy induction and a decrease in viability and survival of prostate cancer cells." (PMID 35317831, 2022). "Studies demonstrate that upstream mediators of autophagy such as MTOR and certain ATGs are tightly regulated by miRNAs in prostate cancer." (PMID 35317831, 2022). "Previous research on preclinical models from other cancers have elucidated a role for mTOR inhibitors in cancers, such as myeloma or prostate cancer." (PMID 35216092, 2022). "Specifically, we propose that CAMKK2 enables metabolic syndrome, which causes increased levels of circulating insulin or some insulin-like molecule that can promote oncogenic mTOR signaling in distant prostate cancer cells." (PMID 35741020, 2022). "In conclusion, the present findings indicated that autophagy induced by CHRM1 mediates migration and invasion targeting Atg5 via AMPK/mTOR pathway in prostate cancer cells." (PMID 35720225, 2022). "Studies have shown that mTOR is overexpressed in prostate cancer, and mTOR inhibitors have shown positive results in the treatment of prostate cancer in phase I clinical trials." (PMID 36132221, 2022).
prostate carcinoma (continued). "Accordingly, there have been intense efforts to develop small molecule inhibitors of PI3K, AKT and the downstream kinase mTOR as drugs to treat cancers including prostate cancer." (PMID 36291720, 2022). "Over the past decades, some small molecule inhibitors of the AKT/PI3K/mTOR pathway have been investigated in prostate cancer." (PMID 36077726, 2022). "Activation of AMPK signaling inhibits the growth of DU145 and PC3 prostate cancer cells by suppressing mTOR/p70S6K." (PMID 36114448, 2022). "In this way, SNHG1 induces PI3K-AKT signaling to induce MTOR expression, resulting in autophagy inhibition, paving the way for survival and proliferation of prostate cancer cells." (PMID 35317831, 2022). "For this reason, the c-Myc expressing Myc-CaP prostate cancer cell line was applied because c-Myc expression reduced the activity of the mTOR inhibitor rapamycin in prostate cancer." (PMID 35582529, 2022). "Acetyl-lupeolic acid, a Boswellia carterii-derived compound, triggers apoptosis in prostate cancer cells by suppressing AKT/mTOR." (PMID 36139919, 2022). "Autophagy inhibition via MTOR signaling induction significantly enhances therapeutic efficacy of docetaxel in prostate cancer treatment." (PMID 35317831, 2022). "Our previous study suggested the reciprocal miR-99b-5p/MTOR (downregulated/upregulated) pairing as a key microRNA-mRNA regulatory component involved in the prostate cancer (PCa) disparities." (PMID 36077039, 2022). "Taken together, our results indicate the potential to therapeutically target KDM5C either alone or in combination with Akt/mTOR-inhibitor in prostate cancer patients by targeting the EMT signaling pathways." (PMID 35454801, 2022). "The results of tens of clinical trials with inhibitors of PI3K, AKT and mTOR in prostate cancer patients have been disappointing with significant adverse effects and little or no efficacy." (PMID 36291720, 2022). "As expected for PI3K pathway inhibition, global gene expression analysis demonstrated that BAY1082439 treatment led to downregulation of mTOR signaling and cell proliferation-related pathways as well as Ki67 expressions in all 4 prostate cancer cell lines." (PMID 35013322, 2022). "Lycopene therapy has mostly been studied in prostate cancer, a malignancy shown to involve mTOR signaling." (PMID 35216092, 2022). "The loss of PTEN, resulting in tumorigenesis or drug resistance due to a hyperactivation of the PI3K/Akt/mTOR pathway, is the second most common genomic aberration in advanced prostate cancer after the androgen-receptor (AR) alterations." (PMID 36077726, 2022). "Increasing evidence has demonstrated that upstream mediators such as AMPK, non-coding RNAs, KLF5, MTOR and others regulate autophagy in prostate cancer." (PMID 35317831, 2022). "Piperine, a natural alkaloid, inhibits the migration of prostate cancer cells via suppressing AKT/mTOR/MMP9 signaling." (PMID 36139919, 2022). "Intriguingly, compared with PC-3 sh-NC cells, PC-3 sh-Atg5 cells failed to restore the expression of p-AMPK and p-mTOR even in the presence of CAR, indicating that CHRM1 activates AMPK/mTOR pathway by targeting Atg5 in the prostate cancer cells." (PMID 35720225, 2022). "Together, GNE-493 inhibited prostate cancer cell growth possibly through the Akt-mTOR-dependent and -independent mechanisms." (PMID 35296639, 2022). "In this review, we summarized the in vivo and in vitro evidence of Tanshinone against prostate cancer and discussed the effect of Tanshinone on nuclear factor kappa-B (NF-κB), AR, and mTOR." (PMID 36080361, 2022).
prostate carcinoma (continued). "In prostate cancer, IL-8 activates the mTOR signaling pathway to defend prostate cancer cells against the oxidative damage induced by GSK-3β." (PMID 36428665, 2022). "Q-6-C-b-D-glucopyranoside, a naturally occurring derivative of quercetin, demonstrated anti-prostate cancer action via blocking the Akt-mTOR pathway through the aryl hydrocarbon receptor." (PMID 36233051, 2022). "MIR32 is another factor that upregulates BECN1 and LC3-II, while downregulating MTOR to induce autophagy and provide radio-resistance in prostate cancer cells." (PMID 35317831, 2022). "A constitutively-active mutant Akt1 restored Akt-mTOR activation but only partially ameliorated GNE-493-induced prostate cancer cell death." (PMID 35296639, 2022). "Meanwhile, miR-381 overexpression suppresses RELN expression, which in turn reduces PI3K/AKT/mTOR signaling pathway activation and hence reduces prostate cancer cell growth and enhances apoptosis and autophagy in these cells." (PMID 36428613, 2022). "Fisetin exhibits a dual function for inhibiting PI3K/AKT and mTOR and promotes cytotoxic autophagy in prostate cancer cells." (PMID 36139919, 2022). "In cancer cells overexpressing the miR-34a show reduced expression of autophagy-related proteins, such as ATG4B, Beclin-1 and LC3B II/I in prostate cancer cells by p-AMPK down-regulation as well as up-regulation of p-mTOR." (PMID 35193115, 2022). "For instance, Smurf1 accelerates PTEN ubiquitination and thus mediates prostate cancer and glioblastoma progression through the mTOR signaling." (PMID 35233069, 2022). "Our results suggest a novel therapeutic possibility for patients with PTEN wild-type PI3K/AKT-mutant prostate cancer based in the combination of PI3K/mTOR blockade with HER2 or mGluR1 inhibitors." (PMID 35086953, 2022). "Conversely, in vitro studies have shown an AR-mediated activation of mTOR independently of PI3K-Akt stimulation in prostate cancer cells stimulated with Dihydrotestosterone (DHT)." (PMID 35011901, 2021). "Increasing evidence from in vitro and animal models studies demonstrates that the PI3K-Akt-mTOR pathway plays a critical role in prostate cancer development and progression." (PMID 35011901, 2021). "The dual PI3K/mTOR inhibitor X480 was shown to inhibit bone metastasis and tumor-induced osteolysis in vivo as well as inhibits prostate cancer-induced osteoclastogenesis and stimulates osteoblast activity in vitro." (PMID 34064589, 2021). "Inhibition of PI3K/AKT/mTOR is a well-established target for cancer therapy, including prostate cancer." (PMID 34578333, 2021). "Relevant connections between the PI3K/Akt/mTOR pathway, cell survival, and prostate cancer (PC) provide a great therapeutic target for PC prevention or treatment." (PMID 34452154, 2021). "We identified “Prostate Cancer”, “MTOR signaling pathway”, “RIG-I-like receptor signaling pathway”, “ERBB signaling pathway”, “JAK-STAT signaling pathway” and “Apoptosis” as the potential functional enriched pathways modulated by LRRK2." (PMID 34217264, 2021). "Here we examined the correlation between YB-1 and CXCL14, and the ERK/AKT/mTOR pathways in prostate cancer." (PMID 34696665, 2021). "Fisetin has been shown to be a dual inhibitor of PI3K/AKT and mTOR in prostate cancer cells and in human NSCLC cells, as well as an inducer of autophagy in pancreatic cancer cells via ER stress- and mitochondrial stress-dependent pathways." (PMID 34575981, 2021).